GPX2 (glutathione peroxidase 2)
Diseases named in the same sentence as GPX2 in open-access papers (continued):
Sharing a sentence is not in itself a finding about the gene and the disease.
tumor (continued). "Consistent with this, we observed that GPX2 protein was particularly enriched in the basal cells of mini-colon tumours." (PMID 38658753, 2024). "MET induction by GPx2 OE was supported by dramatically reduced lung colonisation following tail vein injection of tumour cells into female athymic mice." (PMID 38238426, 2024). "We have previously shown that GPx2 KD stimulates a shift from OXPHOS to aerobic glycolysis in all tumour cell clusters (cluster 0, 1, 2, 3, 4, 6), except for cluster 5 which used OXPHOS and glycolysis." (PMID 38238426, 2024). "In fact, GPx2 KD tumours showed HIF1α upregulation that was accompanied by increased SNAI1, TWIST, N-CAD and decreased E-CAD expression, thus supporting effects of HIF1α on EMT." (PMID 38238426, 2024). "Tumor-derived cell lines are quite commonly used for pre-clinical studies involving the role of GPX2 in CRC." (PMID 39329876, 2024). "Of note, suppression of metastasis and EMT hybrid states by echinomycin in PyMT1/GPx2KD tumours was recapitulated by GPx2 OE or induction in PyMT2 tumours, thus reiterating a strong connection between GPx2 KD, HIF1α, partial EMT, and metastasis." (PMID 38238426, 2024). "Conversely, luminal cluster 2 was increased from 10.23% in control to 13.16% in GPx2 KD tumour, indicative of proliferative activity." (PMID 38238426, 2024). "Using scRNA-seq of the PyMT/GPx2 KD vs PyMT control tumour model, we identified six overlapping luminal clusters and one basal/mesenchymal-like cluster (cluster 3) enriched in EMT genes." (PMID 38238426, 2024). "Conversely, luminal clusters 4 and 5 were reduced from 10.75% and 9.38% in control to 7.87% and 6.69% in GPx2 KD tumour." (PMID 38238426, 2024). "As tiopronin targets several glutathione peroxidases, we corroborated the specific implication of GPX2 in tumour initiation by knocking down its transcript." (PMID 38658753, 2024). "Integration of single-cell transcriptomics between the PyMT/GPx2 KD primary tumour and paired lung metastases unraveled a basal/mesenchymal-like cluster and several luminal-like clusters spanning an EMT spectrum." (PMID 38238426, 2024). "The results showed a weakening of GPX2-positive staining in tumor tissues after 125I seed implantation compared to the control group." (PMID 38914724, 2024). "For example, Domain 0 was predominantly categorized as tumor tissue, as indicated by the marker gene GPX2." (PMID 38819253, 2024). "Apart from scarce pan-leukocyte infiltration in immunologically cold tumors, the metabolic enzyme of GPX2 overexpressed in several smoking-related cold tumors is another novel targetable effector mediating tumor immune escape." (PMID 37252189, 2023). "Our work is also the first to demonstrate the localization of Gpx-2 in tumour tissue at the electron microscopic level using the immunogold labelling method." (PMID 37834097, 2023). "In contrast, Gpx-2 protein showed a marked decrease in immunohistochemical expression, with 16 (72.73%), 7 (10.94%) and 1 (2.56%) tumours showing low levels of expression in G1, G2 and G3, respectively." (PMID 37834097, 2023). "GPX2 maintains low intracellular ROS level, thereby maintaining the clonogenic and metastatic tumour cell populations in CRC." (PMID 37743483, 2023). "The ROS-scavenging enzyme GPX2 is a critical determinant of tumour differentiation, growth, and metastasis in CRC." (PMID 37743483, 2023). "The observed increase in the expression levels of Gpx-2 showed a significant correlation with the histological grade of the tumour as determined with the Chi2 test (p < 0.001)." (PMID 37834097, 2023). "We confirmed the presence of Gpx-2 in the cytoplasm of tumour cells using the immunogold labelling method." (PMID 37834097, 2023). "The gene can also boost Nrf2’s role in promoting the transcription of GPX2, neutralize excessive oxidation production, and prevent tumor cells from being destroyed by oxidants." (PMID 37810778, 2023).
tumor (continued). "The high expression of Gpx-2 was correlated with the histological grade of the tumour (p < 0.001), PCNA immunohistochemical expression (p < 0.001), depth of invasion (p = 0.001) and angioinvasion (p < 0.001)." (PMID 37834097, 2023). "Our results also showed increased gpx2 expression in the tumor tissues of males and females, with important gender differences." (PMID 37761814, 2023). "Next to intestinal stem cells, also many types of tumour cells show upregulation of GPX2 supporting the view that GPX2 expression is specifically enhanced in highly proliferating cells." (PMID 36608588, 2023). "The results of this study indicate a substantial presence of Gpx-2 protein in tumours that were graded G1, G2 and G3." (PMID 37834097, 2023). "After knocking down the levels of GPX2 mRNA, the migration, invasion, and proliferation abilities of tumor cells decreased." (PMID 37810778, 2023). "Specifically, 27.27%, 89.06% and 97.44% of tumours in these grades showed high levels of Gpx-2 protein expression." (PMID 37834097, 2023). "This was supported by IPA upstream regulator analysis of the GPx2 KD tumor, showing activation of mTOR kinase (Z-score = 2.26)." (PMID 35193955, 2022). "In contrast to cluster 5, GPx2 KD stimulates the Warburg effect in all other tumor cell subpopulations (clusters 0, 1, 2, 3, 4, and 6) as shown by inhibited OCR and enhanced glycolysis." (PMID 35193955, 2022). "In contrast to our data supporting a tumor-suppressive function of GPx2, other studies have pointed to protumorigenic effects, implying GPx2 exerts complex biological functions." (PMID 35193955, 2022). "GPX2 keeps intracellular hydrogen peroxide levels low, thus maintaining clone formation and tumor cell numbers." (PMID 36324584, 2022). "We performed clustering analysis of the cells and used uniform manifold approximation and projection (UMAP) to visualize the clusters shared by the GPx2 KD and control tumor." (PMID 35193955, 2022). "To elucidate the biological processes regulated by GPx2, we examined in vivo the effect of GPx2 KD on tumor cell proliferation, angiogenesis, oxidative stress, and hypoxia, all hallmarks of malignancy." (PMID 35193955, 2022). "While laminin (TRITC) was colocalized with endomucin (FITC) in a large fraction of PyMT1 tumor vessels, it was severely impaired in GPx2 KD tumors, with fewer vessels staining for both markers." (PMID 35193955, 2022). "Annotation of the differentially expressed genes by GPx2 KD onto the genes regulating glycolysis in the Ingenuity Knowledge Base predicted enhanced glycolysis in the GPx2 KD tumor." (PMID 35193955, 2022). "Obviously, for the expression level, PRDX1 was strongly expressed in normal tissues, but GPX2 was moderately expressed in tumor tissues." (PMID 35705729, 2022). "Expressions of miR-185 and that of affected genes, such as glutathione peroxidases 2 (GPX2) and selenophosphate synthetase 2 (SEPHS2), decreased considerably in tumor cells grown in selenium-deficient medium." (PMID 36287119, 2022). "The findings suggest GPX2 as a good marker of tumor heterogeneity and provides a basis for future targeted therapy." (PMID 35721499, 2022). "The perfusion ratio or the fraction of endomucin-FITC+ vessels colocalizing with lectin-TRITC, was significantly reduced in GPx2 KD tumors relative to controls, suggesting GPx2 KD in tumor cells impairs vascular perfusion." (PMID 35193955, 2022). "We firstly analyzed the overall differential expression of genes in the GPx2 KD tumor relative to control tumor." (PMID 35193955, 2022). "Analysis of GPx2 mRNA expression from The Cancer Genome Atlas (TCGA) BC datasets (BRCA) revealed that GPx2 was significantly attenuated in the tumor relative to matched normal breast tissue." (PMID 35193955, 2022). "Next, we compared cluster 5 gene expression in the PyMT1/GPx2 KD tumor to that in the control tumor." (PMID 35193955, 2022).
tumor (continued). "In that regard, GPX1, GPX3, and GPX7 expression were found to be decreased in tumor tissues, while the expression of GPX2 and GPX4 was found to be upregulated." (PMID 33228209, 2020). "The Nrf2 stress response transcription factor, which binds to AREs, is an important regulator of tumor cell survival during metastatic progression and regulates a number of antioxidants important in this process, including GPx2." (PMID 32781581, 2020). "In vitro studies suggest that GPx2 exhibits anti-inflammatory properties and inhibits the migration of tumor cells, but also supports the growth of transformed intestinal cells." (PMID 29416634, 2018). "As expected in conditions of redox stress, a lowered SELENOP expression was reported in studies of a small number of German CRA and CRC subjects, while heterogenous GPX2 mRNA and protein expression was observed between the tumor samples." (PMID 30469315, 2018). "GPX2, a selenoprotein, was exclusively expressed in gastrointestinal tract and has an anti-oxidative damage and anti-tumour effect in the progress of tumourigenesis." (PMID 27388201, 2016). "As detected in other tumours, the expression of GPX2 protein was markedly up-regulated within ESCC tumour tissues." (PMID 27388201, 2016). "Collectively, these results suggested that the expression of GPX2 was significantly up-regulated within ESCC tumour tissues." (PMID 27388201, 2016). "Impressively, GPX2 has an anti-inflammatory and anti-tumour effect in the course of the tumorigenesis." (PMID 27388201, 2016). "Even though inflammation was most severe under −Se, −Se GPx2-KO mice had the same tumor size as −Se WT mice." (PMID 23977205, 2013). "In the present study, tumor size was equal in −Se and +Se GPx2-KO mice and significantly decreased with ++Se." (PMID 23977205, 2013). "In order to test the effect of a GPx2-KO on tumor development, mice were challenged six times with AOM and analyzed 16 weeks after the last AOM application." (PMID 23977205, 2013). "On the one hand, GPx2 decreased tumor numbers in an inflammation-triggered colon carcinogenesis model after application of azoxymethane (AOM) and dextran sodium sulfate (DSS) by acting anti-inflammatory." (PMID 23977205, 2013). "GPx2-KO and WT mice on −Se and ++Se diets had similar tumor size, whereas tumors were significantly larger in +Se GPx2-KO than in +Se WT mice." (PMID 23977205, 2013). "In contrast, in the +Se groups tumor numbers were similar in both genotypes but tumor size was larger in GPx2-KO mice." (PMID 23977205, 2013). "GPx2 was up-regulated in dysplastic WT crypts, where it appears to act anti-apoptotic and, thus, supports tumor development." (PMID 23977205, 2013). "Tumor numbers per animal tended to be higher in GPx2 KO mice at all selenium diets and were decreased by supranutritional selenium." (PMID 22654914, 2012). "The results of the CCK-8 assay revealed that, except for Hippo, these inhibitors could mitigate the growth-promoting effect of GPX2 on tumor cells to varying degrees." (PMID 40533443, 2025). "In our study, by identifying GPX2 as a key regulator of lipid synthesis and an apoptosis inducer through various mechanisms, we further confirmed that high GPX2 expression counteracts cisplatin-induced apoptosis and promotes tumor chemoresistance." (PMID 41145471, 2025). "In the tumor immune microenvironment, the role of GPX2 is equally crucial: on the one hand, it may affect immune cell function by regulating the ROS levels of tumor cells themselves." (PMID 41409301, 2025). "There is evidence to suggest that dietary components such as carotenoids may enhance the antioxidant defense system, affect the expression of genes such as GPX2, thereby reducing oxidative damage and inhibiting tumor development." (PMID 41409301, 2025).
tumor (continued). "In a xenograft model of MKN45 cells, compared with the control group, we observed that knockdown of GPX2 inhibited tumor growth and enhanced cisplatin drug sensitivity, further confirming the synergistic promotion of GPX2 knockdown on cisplatin-induced apoptosis." (PMID 41145471, 2025). "Moreover, combination of GPX2 intervention and gefitinib significantly reduced tumor weight as compared with treatment of gefitinib alone." (PMID 40533443, 2025). "High GPx2 expression supports tumor cell proliferation, invasion, and resistance to apoptosis." (PMID 39942544, 2025). "Furthermore, GPX2 levels elevated in tumor tissues compared with normal tissues, while METTL14 levels declined." (PMID 40533443, 2025). "Indeed, we showed that hybrid cells in GPx2 KD primary tumour and lung mets were enriched in p63, thus supporting a critical role in the onset of hybrid populations at both sites." (PMID 38238426, 2024). "IHC analysis detected the expression of GPX2 in tumor tissues." (PMID 38914724, 2024). "However, in agreement with feature plots, GPx2 KD tumours harboured areas expressing both E and M markers involving KRT14 (basal) and KRT8 (luminal) relative to control tumours expressing only KRT8 (Areas 1, 3, 4)." (PMID 38238426, 2024). "We next tested whether GPx2 KD enhances metastasis via promotion of the hybrid E/M tumour phenotype." (PMID 38238426, 2024). "Interestingly, GPx2 KD tumours also harboured areas that were either KRT14 or KRT8 positive (Area 2)." (PMID 38238426, 2024). "Interestingly, PyMT2 tumours were enriched in KRT8/KRT14 or E-CAD/VIM hybrid areas as compared to GPx2 OE tumours which expressed either KRT8 or E-CAD, indicative of mesenchymal to epithelial transition (MET)." (PMID 38238426, 2024). "In light of these findings, we sought to investigate whether GPx2 KD promotes EMT dynamics at the single cell level at the primary tumour and distant sites to unravel unique subpopulations and/or oncogenic drivers governing metastasis." (PMID 38238426, 2024). "ROS, as one of the most important metabolites after GPx2 knockdown, modulates the tumor microenvironment, affecting various stromal cells that provide metabolic support, blood supply, tumor immune response and tumor metastasis." (PMID 37138031, 2023). "Altogether, this supports the idea that sex steroids may be involved in the GPx-2 tumor-related functions." (PMID 37761814, 2023). "Notably, we identified strong expression of Gpx-2 protein in 27% of G1 tumours, 89% of G2 tumours and 98% of G3 tumours." (PMID 37834097, 2023). "Tumors with GPX2 overexpression have a more incompetent tumor immune environment." (PMID 37252189, 2023). "GPx2 knockdown suppressed tumor proliferation in gastric xenograft tumor models." (PMID 37138031, 2023). "In addition, they showed that GPX2 plays an important role in tumor development, such as the survival of neoplastic cells against ROS, favoring the growth of established tumors and promoting the development of neoplastic masses." (PMID 37075346, 2023). "IHC staining also indicated this regulatory effect of ACVRL1 on GPX2 in tumour xenografts." (PMID 37743483, 2023). "Similarly, Gpx2- or Selenof-KO mice developed fewer ACFs than WT mice after AOM treatment; in the case of Gpx2-KO mice, this corresponded with a decrease in tumor numbers." (PMID 37166989, 2023). "Glutathione peroxidase-2 (GPx2) plays various roles in tumor progression and patient survival." (PMID 37138031, 2023). "In addition, the expression of PRDX2 and PRDX5 in the GPx2 KD tumor was increased by 1.3-fold (logFC = 0.4) and catalase by 1.2-fold (logFC = 0.27), whereas the expression of SOD2 was unchanged." (PMID 35193955, 2022). "In fact, treatment of GPx2 KD tumor-bearing mice with echinomycin, a drug that inhibits HIF1α, reduced VEGFA expression and tumor growth, while improving vessel maturation, underscoring the effect of GPx2 loss on vascular malfunction." (PMID 35193955, 2022).
tumor (continued). "Of note, these metabolic changes, indicated by GLUT1 and p-AMPK expression, were maintained in similarly sized tumors, thus supporting effects that may be due to increases in tumor bulk by GPx2 KD." (PMID 35193955, 2022). "Finally, it is noteworthy that EIF2 signaling, which promotes translation initiation, was inhibited in three of the seven clusters in the GPx2 KD tumor (Z-score < −2)." (PMID 35193955, 2022). "To determine whether GPx2 regulates malignant progression in vivo, we tested whether GPx2 KD in mouse and human BC cells affects tumor growth or metastasis." (PMID 35193955, 2022). "However, over-GPX2 promoted PCa cell proliferation and invasion and inhibited apoptosis, indicating that over-GPX2 promoted tumor progression to a certain extent." (PMID 36312753, 2022). "Indeed, PyMT1/GPx2 KD tumor cells exhibited striking changes in OCR that led to stark reductions in basal respiration, maximal respiration, and spare respiratory capacity relative to control cells." (PMID 35193955, 2022). "We next investigated whether metabolic reprogramming by GPx2 KD was uniform in all the tumor cell clusters." (PMID 35193955, 2022). "Importantly, analysis of the differentially expressed genes in the GPx2 KD tumor relative to control tumor revealed changes in mRNA expression of other members of the GPx family." (PMID 35193955, 2022). "Together, these findings underscore a robust suppressive effect of GPx2 on tumor progression." (PMID 35193955, 2022). "The TXNRD1, GPX1, and GPX2 genes may exert dual effects in tumor mutagenesis and development, while the TXNRD1, GPX1, GPX2, and GPX3 genes were found to be related to drug sensitivity or the formation of drug resistance." (PMID 33706760, 2021). "However, overexpression of GPx2 stimulated tumor growth, as well as differentiation, indicating a redox regulatory function of GPx2 in controlling tumorigenesis." (PMID 32414091, 2020). "Furthermore, we found three lipid-metabolism related genes HMGCS2, GPX2 and CD36 associated with the tumor immune microenvironment were significantly correlated with prognosis." (PMID 31074374, 2019). "Knock-down of Gpx2 significantly inhibited tumor growth of BC31 cells as compared to the NC." (PMID 29662611, 2018). "Therefore, the expression of GPX2 protein was significantly related to the tumour histological grade of ESCC." (PMID 27388201, 2016). "GPX2 may play an important role in anti-tumour within ESCC tumour tissues, while ESCC with a loss expression of GPX2 protein is prone to progress to the poor differentiated ESCC." (PMID 27388201, 2016). "In this study, immunohistochemistry (IHC) results of triple samples of 60 patients with ESCC showed that the significant higher expression level of GPX2 protein was detected in ESCC tumour tissues compared with non-tumour including PN and DN tissues (P < 0.001)." (PMID 27388201, 2016). "GPx2-knockout (KO) and wild-type (WT) mice were adjusted to an either marginally deficient (−Se), adequate (+Se), or supranutritional (++Se) selenium status and were treated six times with azoxymethane (AOM) to induce tumor development." (PMID 23977205, 2013). "The decrease in tumor development could be attributed to the efficient elimination of damaged or premalignant epithelial cells in GPx2-KO mice." (PMID 23977205, 2013). "On the other hand, cytotoxic T lymphocytes (CTLs) require precise ROS regulation when delivering cytotoxic particles through immune synapses, so the expression of GPX2 in T cells or ROS levels in the tumor microenvironment may directly affect the killing efficiency of CTLs." (PMID 41409301, 2025). "Therefore, the two-sided nature of GPx2 depends on the tumor type and stage of disease." (PMID 38483584, 2024). "Inhibiting GPX2 could increase ROS levels and enhance the anti-tumor effect of lenvatinib." (PMID 38914724, 2024).